RN7SKP141 (RN7SK pseudogene 141)
Gene: Miscellaneous RNA gene on chromosome 2 (136,390,332 to 136,390,669, forward strand). Ensembl gene ENSG00000251976.
Homologues: Orthologues: chimpanzee 7SK (99% identical), mouse Gm55664 (40% identical), mouse Gm54997 (39% identical), guinea pig 7SK (39% identical), mouse Gm54777 (12% identical). Paralogues in human: RN7SKP79 (49% identical), RN7SKP208 (48% identical), RN7SKP124 (48% identical), RN7SKP6 (48% identical), 7SK (48% identical), RN7SKP103 (47% identical), RN7SKP146 (47% identical), RN7SKP278 (47% identical), RN7SKP3 (47% identical), RN7SKP149 (47% identical), RN7SKP162 (47% identical), RN7SKP48 (47% identical), and 284 more.